PPARG (peroxisome proliferator activated receptor gamma)
Diseases named in the same sentence as PPARG in open-access papers (continued):
Sharing a sentence is not in itself a finding about the gene and the disease.
Insulin resistance (continued). "Furthermore, the present authors have recently revealed that PPARG is the first gene abnormally expressed as a result of induction of insulin resistance, which proves its crucial role in the regulation of insulin sensitivity." (PMID 35684107, 2022). "In addition, PPARG agonists represent an option for the treatment of insulin resistance in type 2 diabetes." (PMID 35684107, 2022). "The polysaccharides could reduce palmitic acid-induced insulin resistance in vitro by activating the expression of peroxisome proliferator-activated receptor-gamma (PPAR-γ)." (PMID 36160715, 2022). "SIRT1 binds and deacetylates PPARγ, which helps recruit the BAT program coactivator PRDM16 to PPARγ, leading to selective induction of BAT genes associated with browning of white adipocytes and repression of visceral WAT genes associated with insulin resistance." (PMID 35743009, 2022). "Moreover, PPARγ agonists reduce the inflammation mediators that promote insulin resistance and trigger an increase in circulating adiponectin levels with a positive outcome for insulin sensitivity and a decreasing effect on glucose production in the liver." (PMID 34827690, 2021). "For example, miR-27a derived from adipose tissue may inhibit PPARγ and its downstream genes, and play a key role in the occurrence of insulin resistance induced by obesity." (PMID 33959041, 2021). "Deacetylation of Lys268 and Lys293 on PPARγ induced by SIRT1 recruits the BAT program coactivator Prdm16, leading to the selective induction of BAT genes and repression of WAT genes associated with insulin resistance." (PMID 34421358, 2021). "Therefore, the modulation of Pparγ activity and expression can provide alternative therapeutic strategies against insulin resistance and diabetes." (PMID 33804020, 2021). "The emerging role of JNK at the intersection between IRS inactivation and PPARγ downregulation suggests that JNK could be a potential key target in the search of new medicines to control insulin resistance and T2D." (PMID 34680177, 2021). "In addition, pterostilbene is known to reduce expression of Peroxisome Proliferator Activated Receptors γ (PPARγ) involved in the starting of insulin resistance and dyslipidaemia." (PMID 34630615, 2021). "In contrast, decreased PPARγ activity is also reported to improve insulin resistance." (PMID 33494317, 2021). "In clinical practice, PPARγ agonists such as pioglitazone and rosiglitazone have been used for a long time for the management of insulin resistance, which decreases the activation of MCP1, IL-6 and TNF and regulates the synthesis of adiponectin (anti-inflammatory molecule)." (PMID 34679777, 2021). "Of note, insulin resistance has been linked to the abnormal expression of neutrophil elastase, a key enzyme for elastin fragmentation; in turn, EDPs have been involved in the development of insulin resistance in mice by a peroxisome proliferator-activated receptor-γ (PPARγ)-dependent pathway." (PMID 34439505, 2021). "Moreover, 25(OH)D regulates the metabolism of free fatty acids (FFAs) through its direct action on peroxisome proliferator-activated receptor gamma (PPAR-g), increasing FFA-caused insulin resistance in vitro." (PMID 34444431, 2021). "The methylation of the PPARG promoter was higher by about two times after 48 h (p = 0.006) and three times after 72 h (p = 0.024) of insulin resistance induction compared to adipocytes with proper insulin sensitivity; this correlated with the expression of this gene in experimental adipocytes." (PMID 34207541, 2021). "Moreover, Creb1 has been shown to aggravate insulin resistance by stimulating the expression of the bZiP factor ATF3 which represses Pparγ expression and inhibits adipocyte differentiation." (PMID 33912553, 2021).
Insulin resistance (continued). "To address how PPARγ agonism can improve cognition in the absence of insulin resistance, we and others have described neuronal signaling pathways modulated by PPARγ agonism that are not directly associated with glucose uptake and insulin sensitivity." (PMID 33382528, 2021). "Based on that we believed that, VGVAPG peptide affecting the PPARγ pathway could first prevent the maturation of preadipocytes and next make it difficult to break insulin resistance." (PMID 32463311, 2020). "Research addressing whether the beneficial effect of PPARγ agonists on depressive symptoms is correlated with changes in insulin resistance level has been equivocal." (PMID 32971941, 2020). "In addition, PPARγ can affect insulin sensitivity by regulating adipocyte hormones, cytokines, and proteins that are involved in insulin resistance." (PMID 32047529, 2020). "Alternatively, pathways other than insulin resistance may mediate the antidepressant properties of PPARγ agonists." (PMID 32971941, 2020). "Expression of PPARγ was found to increase with insulin resistance." (PMID 32815547, 2020). "PPARγ, which is mainly expressed in adipose tissue and the immune system, is closely related to the differentiation of adipocytes, glycolipid metabolism and insulin resistance." (PMID 32821266, 2020). "Furthermore, adipose-specific NAMPT is closely related to insulin resistance in the adipose tissue, liver, and skeletal muscle through the regulation of PPARγ and adiponectin." (PMID 32334629, 2020). "The activation of PPARγ in vascular smooth muscle cells resulted in improved inflammation, coronary insulin resistance, and upregulation of adiponectin receptor expression and might even improve the health of patients with T2D." (PMID 31918918, 2020). "A noteworthy aspect related to PPARγ is its impact on insulin resistance." (PMID 31908775, 2020). "Here, we investigate how this phosphorylation may disturb the interaction between PPARγ and some coregulator proteins as a new mechanism that may leads to insulin resistance." (PMID 33329381, 2020). "The treatment with PPARγ agonists is a clinical approach used to treat insulin resistance." (PMID 31908775, 2020). "Due to the fact that many diabetic patients suffer from atherogenic lipid abnormalities and insulin resistance, ligands that may stimulate both PPARα and PPARγ could be efficaciously used in obese patients with type 2 diabetes." (PMID 33255206, 2020). "Consistently, dominant–negative mutations in human Pparγ causes metabolic syndrome, insulin resistance, and diabetes at a young age." (PMID 33198317, 2020). "However, treatment with small-molecule pioglitazone, a PPARγ agonist, attenuated insulin resistance in patients with NAFLD and NASH53, but increased WAT and BW volumes." (PMID 32792584, 2020). "Moreover, PPARγ regulates the metabolic processes, such as insulin resistance (IR), inflammation, and gluconeogenesis, indirectly affecting lipid metabolism in the liver (Table A1)." (PMID 32272794, 2020). "The phosphorylation of PPARγ at Ser273 by Cdk5 decreases the expression of adiponectin through an unknown mechanism, leading to development of insulin resistance." (PMID 31910742, 2020). "Additionally, severe insulin resistance is found in generalized and partial lipodystrophy syndromes associated with pathogenic variants in AGPAT2, LMNA, and PPARG." (PMID 33210059, 2020). "For example, miR-27a can repress adipogenesis by targeting PPARγ, and recent studies demonstrated that adipocyte-derived exosomal miR-27a could be assimilated by myocytes triggering insulin resistance in skeletal muscle through repression of PPARγ." (PMID 33297338, 2020). "Furthermore, adiponectin ameliorates insulin resistance by mediating the biological effects of peroxisome proliferator-activated receptor-gamma (PPARγ)." (PMID 30791536, 2019).
Insulin resistance (continued). "Therefore, drugs that improve insulin resistance or activate PPARγ in the brain can theoretically be beneficial in preventing Alzheimer’s disease or dementia." (PMID 31085804, 2019). "Liver PPARγ seems to protect other tissues from triglyceride accumulation and insulin resistance." (PMID 31121839, 2019). "Thus, ROSI reversed whole body insulin resistance and had direct, local effects on PPARγ in the liver." (PMID 29795456, 2019). "Therefore, DBZ-mediated PPARγ activity improves high-fat diet-induced dysbiosis, weight gain, and insulin resistance in diabetic mice." (PMID 30658440, 2019). "Furthermore, these dysfunctions were accompanied by increased expression of peroxisome proliferator-activated receptor gamma (PPARγ) and severe insulin resistance in the liver." (PMID 31338065, 2019). "Though there might be intrahepatic insulin resistance in these mice, the whole-body insulin sensitivity was presumably increased due to the therapeutic effect of the PPARγ agonist." (PMID 30871156, 2019). "In summary, the present study demonstrated that the widely used traditional Chinese medicinal formula “Tangduqing granules” was capable of reversing insulin resistance and lipid metabolism disorder in diabetic rats, at least partly through coordinated regulation of PPARγ and DGAT2 signal molecules." (PMID 31019978, 2019). "RSG, as a member of the thiazolidinediones (TZDs) family, which is the ligand of the PPARγ, has been currently investigated for the diseases where insulin resistance may be an important factor." (PMID 30947684, 2019). "On the other hand, it has been reported that the modulation of PPARγ activity by selective PPAR modulators reduced insulin resistance and caused no side effects." (PMID 31878261, 2019). "Risk alleles like FTO, ADIPOQ, INSR, IRS1, IRS2, PPARG, CAPN10 may leave individuals more vulnerable to insulin resistance and/or adiposity (which can result in peripheral insulin resistance), leading to high circulating insulin." (PMID 31367382, 2019). "Taken together, the ATX-LPA pathway may contribute to obesity-induced insulin resistance by impairing PPARγ expression and activity." (PMID 29570618, 2018). "In this study, mouse fibroblast 3T3‐L1 cells were used to investigate whether DHM alleviates insulin resistance by inhibiting PPARγ phosphorylation at serine 273 via the MEK/ERK pathway." (PMID 29160030, 2018). "In the adipose tissue, one such outcome is the defective activation of PPARγ which leads to an anomalous distribution of fat and increased expression of inflammatory adipokines, further enhancing inflammation and insulin resistance; thus, creating a vicious cycle." (PMID 29678181, 2018). "Nevertheless, PPARγ is still one of the most important targets for the treatment of insulin resistance and type 2 diabetes, and novel strategies to modulate PPARγ activity to enhance its beneficial effects and reduce unwanted adverse effects are strongly anticipated." (PMID 30079233, 2018). "DIO in mice is also associated with drastically reduced WAT Treg numbers, which were reverted by treatment with the PPARG agonist pioglitazone as were glucose intolerance and insulin resistance in WT mice but not in mice harbouring PPARG-deficient Tregs." (PMID 30158466, 2018). "Based on our findings demonstrating PPARγ activation by XBP1s, we investigated whether XBP1s could improve insulin resistance induced by treating adipocytes with palmitate (200 μM, 24 h), a well-known in vitro model for studying insulin resistance." (PMID 30111834, 2018). "A Chinese medicine, Astragalus polysaccharides, could attenuate TNFα-induced insulin resistance by inhibiting miRNA-721 expression, activating PPARγ, and enhancing PI3K/Akt signalling in 3T3-L1 adipocytes." (PMID 30622558, 2018). "However, the young skeletal muscle of PPARγ-deficient mice remained responsive to the TZD treatment, despite a high-fat diet-induced hepatic insulin resistance and excess adiposity." (PMID 29747466, 2018).
Insulin resistance (continued). "Furthermore, this approach is clinically relevant, as drugs such as rosiglitazone and pioglitazone are used to treat diabetes and/or insulin resistance through their agonistic effect on peroxisome proliferator activated receptor-gamma (PPAR-γ)." (PMID 29023424, 2017). "TNF-α, PPARγ, and ERK are implicated in insulin resistance in metabolic syndrome." (PMID 29340106, 2017). "Our results suggested that STAMP2 gene overexpression may improve insulin resistance via attenuating angiogenesis in epididymal and brown adipose tissues through the PPARγ/CD36 signalling pathway." (PMID 28631352, 2017). "In brief, PPARγ is predominantly present in adipose tissue and macrophages and functions to repartition fatty acids (FAs) to adipose tissue from muscle, liver, and circulation, thus improving insulin resistance." (PMID 29056962, 2017). "Thus, the modulation of BMP signal transduction regulating PPARγ and its target genes in adult tissues harbors a great potential to treat insulin resistance." (PMID 29222456, 2017). "The molecular mechanism of most PPARγ mutations, related to lipodystrophy and insulin resistance, is not clear and the structural reason for the decrease in functional activity of PPARγ variants has been identified in the case of F360L and V290M." (PMID 28208577, 2017). "Here, for the first time, we provide evidence that APL could improve insulin resistance, partially through activating PPARγ and subsequently regulating FGF21-AMPK signaling pathway." (PMID 27391974, 2016). "Our results indicated, for the first time, that APL maybe served as a PPARγ agonists and improved insulin resistance partially via activation of PPARγ and subsequent regulation of FGF21- AMPK signaling pathway." (PMID 27391974, 2016). "In the search for novel PPARγ agonists, we screened a library of natural products and identified podophyllotoxin, which is extracted from plants of the genus Podophyllum, and found that it exhibits partial activation of PPARγ and the capacity to reverse insulin resistance." (PMID 27853282, 2016). "Thiazolidinediones (TZD), such as rosiglitazone, represent a class of antidiabetic drugs that are capable of improving insulin resistance through activation of the nuclear hormone receptor PPARγ, which serves also as a master regulator of late adipocyte maturation." (PMID 27992530, 2016). "They found that the risk loci could be subdivided into five clusters including one cluster with four loci, PPARγ, KLF14, IRS1 and GCKR, associated with insulin resistance." (PMID 27312935, 2016). "The increased expression of PPARγ in liver may be a compensatory response to weaken the insulin resistance." (PMID 27827939, 2016). "Thus, it becomes obvious here that PPARγ exert regulatory functions at the crossroads between insulin resistance, inflammation and adipocyte differentiation." (PMID 27992530, 2016). "Collectively, we hypothesized that APL maybe an approaching PPARγ agonist that beneficially improved insulin resistance." (PMID 27391974, 2016). "For example, phthalates are known to bind to peroxisome proliferator-activated receptor gamma (PPAR-γ), which could upregulate adipocyte production and, in an environment with excess caloric intake, could contribute to insulin resistance." (PMID 27079661, 2016). "Therefore, using a PPARδ specific ligand, GW0742, can activate the protective effects from hypertriglyceridemia and insulin resistance as what PPARα and PPARγ do but alternatively prevents the sequel of edema and fluid retention induced by PPARγ." (PMID 27519769, 2016). "Collectively, these findings above indicated that APL- mediated insulin resistance improvement maybe, at least in part, be attributed to the activation of PPARγ." (PMID 27391974, 2016). "In addition, PPARγ agonists were associated with the development of hepatic steatosis in rodents, whereas several PPARγ antagonists were shown to ameliorate insulin resistance and hepatic steatosis, accompanied by reduced body weights." (PMID 27176632, 2016).
Insulin resistance (continued). "Moreover, PPARγ is also responsible for the improvement of insulin resistance and plays an important role in glucose homeostasis." (PMID 27069498, 2016). "Interestingly, adipose tissue specific Cdk5 KO mice have increased PPARγ phosphorylation and insulin resistance due to ERK dependent phosphorylation." (PMID 27483259, 2016). "TonEBP is an attractive therapeutic target for insulin resistance in lieu of PPARγ agonists." (PMID 26042523, 2015). "Furthermore, certain natural PPARγ modulators, such as conjugated linoleic acid, can increase PPARγ expression, resulting in improved insulin resistance and glucose tolerance." (PMID 26228038, 2015). "We have recently shown that insulin resistance in adipocytes is highly selective for GLUT4 trafficking, and so the ability of PPARγ agonists to reverse insulin resistance would seem to reflect an important role for PPARγ in regulating components of the GLUT4 trafficking process." (PMID 26240143, 2015). "Inflammatory cytokines, such as TNF-α, IL-6, and IL-8, are involved in the second hit stage, mediate steatohepatitis in patients with NAFLD, and can be regulated by PPARγ, which is not only related to anti-inflammatory effects, but also close to improving insulin resistance." (PMID 26221176, 2015). "However, in recent years, studies have demonstrated that a PPARγ gene knockout or intermediate depression of PPARγ activity can relieve the insulin resistance induced by a high fat diet." (PMID 25574213, 2015). "The ability of Bexarotene to modulate PPARγ may contribute to the beneficial effects observed in animal models of insulin resistance and Alzheimer's disease." (PMID 26451138, 2015). "Recently, it was shown that cyclin-dependent kinase 5 (CDK5)-mediated phosphorylation of PPARγ may be involved in the pathogenesis of insulin resistance and glucose-lowering effects, which provides a new angle to understand the mechanisms of PPARγ activation." (PMID 25827822, 2015). "TUSC5 expression was necessary but insufficient for PPARγ-mediated reversal of insulin resistance." (PMID 26240143, 2015). "However, the breadth of responses to TUSC5 knockdown and because TUSC5 is required for PPARγ-mediated reversal of insulin resistance suggest a longer term role in modulating insulin responses in adipocytes." (PMID 26240143, 2015). "Moreover, results suggest that the mitochondrial function associated with aerobic fitness and insulin resistance is deeply affected by the expression of coactivators (PGC-1α and PGC-1β) of the PPARG." (PMID 25879043, 2015). "In parallel with that, gender differences were detected in response to PPARG-agonist therapy in patients with T2D which might indicate different mechanisms for insulin resistance in men and women." (PMID 26363598, 2015). "We next determined whether TUSC5 was necessary for the reversal of TNFα-induced insulin resistance by the PPARγ agonist rosiglitazone." (PMID 26240143, 2015). "PPARγ not only has anti-inflammatory effects, but also can effectively improve insulin resistance." (PMID 26221176, 2015). "Furthermore, Tusc5 is a PPARγ target gene, and we provide evidence that TUSC5 is required for PPARγ agonism to overcome adipocyte insulin resistance." (PMID 26240143, 2015). "In generalized linear regression analyses adjusted for age, sex and diabetes, PPARG His447His allele T was associated with none of the markers of insulin resistance overall and by diabetes status." (PMID 25197274, 2014). "PPARγ agonist-induced increase of adipocytes may result in the amelioration of insulin resistance partly through augmentation of fat storage in adipocytes." (PMID 24516558, 2014). "Studies have demonstrated that cis-9, trans- 11 CLA increased the expression of PPARγ, whose down-regulation may lead to insulin resistance." (PMID 25534067, 2014).